SNHG1 (small nucleolar RNA host gene 1)
Diseases named in the same sentence as SNHG1 in open-access papers (continued):
Sharing a sentence is not in itself a finding about the gene and the disease.
cancer (continued). "It seems promising to continue exploring such interactions, which will better elucidate the effect of an aberrant expression of SNHG1 in the vast array of signaling pathways relevant to cancer progression." (PMID 39200161, 2024). "SNHG1 is also able to influence glucose metabolism in cancer cells, by accelerating the rate of glucose uptake and production of lactate, known as the Warburg effect." (PMID 39200161, 2024). "SNHG1 is a novel oncogenic lncRNA located on chromosome 11, and accumulating evidence has demonstrated that SNHG1 is upregulated in various types of cancers, often promoting tumorigenesis and tumor progression." (PMID 38879516, 2024). "SNHG1 itself is also known to sponge miRNAs in various cancers, including RCC, where it promotes proliferation, invasion, metastasis formation and immune escape." (PMID 38741178, 2024). "In this review, we have summarized the role and molecular mechanism of SNHG1 in the development of various cancers." (PMID 37684619, 2023). "Data from the Gene Expression Profiling Interactive Analysis 2 database indicated that SNHG1 is highly expressed in pan-cancer." (PMID 37684619, 2023). "In an oncogenic role, the SNHG1 expression is increased in various cancers, which has immense application prospects in the diagnosis, treatment, and prognosis of malignant tumors." (PMID 37684619, 2023). "SNHG1 utilizes complex molecular functions and cellular mechanisms to play its role in cancer progression." (PMID 37684619, 2023). "Numerous studies conducted in recent years have noted that SNHG1 plays an oncogenic role in various cancers." (PMID 37684619, 2023). "In patients with NSCLC, the expression of SNHG1 was found to be significantly increased in cancer cells." (PMID 37684619, 2023). "Some studies have assessed the expression of SNHG1 using quantitative real-time polymerase chain reaction and reported a significant upregulation of SNHG1 in cancer tissues and cell lines." (PMID 37684619, 2023). "The quiescent (G0) population expresses lower levels of SNHG1 than the G1 or S/G2/M populations, suggesting SNHG1 has a function in cycling cancer cells." (PMID 37464317, 2023). "Further information regarding the biological activity of SNHG1 in cancer is difficult to ascertain, due to the literature being corrupted by fabrication of papers for profit." (PMID 37464317, 2023). "SNHG1 is one of the most important regulatory RNAs in human cancer, acting as a competing endogenous RNA." (PMID 37742230, 2023). "No study has yet revealed the mechanisms of C1orf229, MCPH1-AS1, PRR26, and SNHG1 in PCa or other malignant tumors." (PMID 36561322, 2022). "The lncRNA SNHG1 contributed to NSCLC tumorigenesis and progression via the miR-101-3p/SOX9/Wnt/β-catenin axis, whereas depletion of SNHG1 induced cell apoptosis through inactivation of Wnt/β-catenin signalling, thereby inhibiting cancer proliferation." (PMID 35379783, 2022). "In ovarian cancer, SNHG1 stimulates tumor progression by enhancing cancer cell epithelial-mesenchymal transition (EMT) and invasiveness." (PMID 35836822, 2022). "The lncRNA small nucleolar RNA host gene 1 (SNHG1) is a tumor-promoting factor and recent studies have revealed its role in cancer progression." (PMID 35236381, 2022). "This is distinct from the research results related to cancer cells, revealing that the regulatory effect of SNHG1 on cell proliferation is complicated." (PMID 35841022, 2022). "SNHG1 (small nucleolar RNA host gene 1) is a new emerging lncRNA located on chromosome 11 that plays a key role in cancer." (PMID 35317831, 2022). "Small nucleolar RNA host gene 1 (SNHG1) is increased in various diseases and plays an oncogenic role in cancer." (PMID 34621163, 2021). "We found that SNHG1 was overexpressed in our pan-cancer analysis and correlated with poor prognosis, including that of NSCLC." (PMID 34858987, 2021).
cancer (continued). "Our study evidenced both in vitro and in vivo that SNHG1 knockdown impeded cancer progression and tumor metastasis through downregulation of Snail." (PMID 34095464, 2021). "SNHG1 knockdown delayed cancer progression both in vitro and in vivo by upregulating miR-376a and downregulating FOXK1 and Snail." (PMID 34095464, 2021). "Recently, many studies have unveiled the crucial role of SNHG1 in various cancer tumorigeneses and progressions." (PMID 34917510, 2021). "LncRNA small nucleolar RNA host gene 1 (SNHG1) is a long-chain, non-coding RNA associated with EMT in cancer cells." (PMID 32423385, 2020). "Some other miRNAs, such as miR-382-5p, miR-199-3p, and miR-195, have also been suggested as the target of SNHG1, which likely also play important parts in human cancer." (PMID 32802839, 2020). "In many of these cancer types, high SNHG1 expression is correlated with poor prognosis and lower progression-free survival." (PMID 33333852, 2020). "Long non-coding RNA small nucleolar RNA host gene 1 (SNHG1) has been reported to be involved in human diseases, including cancer." (PMID 32497022, 2020). "The carcinogenesis function of SNHG family in cancers has been widely reported, and the participation of SNHG1 and SNHG7 in ESCC has been researched, so we focused on SNHG12 in our research." (PMID 32239639, 2020). "As a newly discovered lncRNA, lnc-SNHG1 is localized at 11q12.3, and has been shown to be upregulated in many malignant tumors." (PMID 33302997, 2020). "LncRNA small nucleolar RNA host gene 1 (SNHG1) sponges the action of the number of miRNAs in cancer cells; similarly, lncRNA also plays an important role in the differentiation of osteoblasts and osteoclasts." (PMID 33281877, 2020). "Accumulating evidence showed that dysregulation of SNHG1 played crucial roles in numerous human cancers." (PMID 32802839, 2020). "The relationship between SNHG1 expression and metastasis or prognosis in malignant tumors was investigated in this meta-analysis." (PMID 31008944, 2019). "LncRNA-SNHG1 (small nucleolar RNA host gene 1), located in 11q12.3, is expressed in broad ranges of cancer tissues." (PMID 31391030, 2019). "SNHG1 is widely distributed in the body and participates in the regulation of proliferation, invasion and metastasis of many types of cancer cells including HCC." (PMID 31053148, 2019). "Previous studies have reported that the lncRNA small nucleolar RNA host gene 1 (SNHG1) is involved in multiple human malignant tumors, while its expression and role in AML is still unexplored." (PMID 31615767, 2019). "Long noncoding RNA (lncRNA) small nucleolar RNA host gene 1 (SNHG1) functions as an oncogene in various human cancers." (PMID 31336999, 2019). "Depletion of SNHG1 enhanced the anti-cancer activities of sorafenib against SR-HCC cells that were refractory to sorafenib-induced proliferation inhibition and apoptosis in vitro and in animal experiments." (PMID 31053148, 2019). "Studies have reported that SNHG1 can promote cell proliferation, invasion and metastasis, and inhibit cell apoptosis in multiple human cancers such as esophageal, liver, gastric, lung, colorectal and prostate cancer." (PMID 31615767, 2019). "The present meta->analysis is to analyze existing data to reveal potential clinical application of SNHG1 on cancer prognosis and tumor progression." (PMID 31391030, 2019). "In recent years, it has been found that SNHG1 is involved in carcinogenesis of human cancer by activating different signaling pathways." (PMID 31383786, 2019). "The functions of long (>200 nt) non-coding RNA (lncRNA) small nucleolar RNA host gene 1 (SNHG1) have only been investigated in cancer biology." (PMID 31693735, 2019). "Then, we observed that miR-101 target genes (c-Fos, ZEB1 and Mcl-1) known to promote cancer progression were significantly downregulated in AML cells with SNHG1 knockdown." (PMID 31615767, 2019).
cancer (continued). "First, mRNA expression of SNHG1 in various cancers was determined by the analyzing the NCI-60 cell line microarray dataset in R2 microarray analysis and visualization platform." (PMID 29416759, 2018). "The small nucleolar RNA host gene (SNHG1, GenBank accession ID:23642), a novel non-coding RNA localized at 11q12.3, has exhibited oncogenic role in diverse cancer." (PMID 29340086, 2017). "SNHG1 expression was also up-regulated in cancer tissues compared to normal counterparts in LUAD and LUSC (P < 0.05)." (PMID 28147312, 2017). "Recently, the lncRNA small nucleolar RNA host gene (SNHG1) has been exhibited to be upregulated, which plays a crucial role in the development and prognosis of several cancers." (PMID 29340086, 2017). "SNHG1 is highly expressed as an oncogenic lncRNA in several cancers." (PMID 41507135, 2026). "In addition, SNHG1 fosters cancer cell growth by inhibiting miR-195 and miR-199a, while also facilitating cancer invasion through its direct interaction with the PP2A catalytic subunit, ultimately triggering autophagy." (PMID 38365726, 2024). "Numerous studies have demonstrated that SNHG1 is upregulated in various types of cancers." (PMID 38879516, 2024). "In addition, aberrant expression of SNHG1 contributes to the proliferation, metastasis, migration and invasion of cancer cells." (PMID 38879516, 2024). "SNHG1 was initially identified as a cancer-related lncRNA by several studies." (PMID 36194366, 2023). "Recently, SNHG1 has been shown to be involved in many cancers." (PMID 36194366, 2023). "Moreover, overexpressed SNHG1 acts a crucial function in cancer progression, invasion, and metastasis in multiple malignancies, including HCC." (PMID 36899391, 2023). "SNHG1 may have potential applications in cancer diagnosis, treatment, and prognosis, but its clinical use is fraught with challenges." (PMID 37684619, 2023). "SNHG1 is an oncogenic gene that has been validated by numerous cancer researchers." (PMID 37686677, 2023). "SNHG1 is present as an oncogene in most types of cancer and is overexpressed in various cancers." (PMID 37684619, 2023). "The biology of lncRNAs such as SNHG1 in cancer is an area that requires increased study." (PMID 37464317, 2023). "The function and expression of SNHG1 in GC differ from those in other cancers." (PMID 37684619, 2023). "Collectively, these findings allude that SNHG1 may enhance the response of cancer cells to conventional therapeutic regimens by acting as a target." (PMID 37684619, 2023). "A number of studies have demonstrated that SNHG1 serves as an oncogene in various cancer types." (PMID 36130928, 2022). "LncRNAs SNHG16 and SNHG1 have been proven to regulate the cancer immune microenvironment." (PMID 35646635, 2022). "LncRNA Small nucleolar RNA host gene 1 (SNHG1) is a lncRNA that belongs to the Small Nucleolar RNA host gene (SNHG) family, comprising more than 20 members, many of which have been found associated with cancer progression." (PMID 36361952, 2022). "In addition, SNHG1 regulated the translation pathway of E-cadherin by reducing the expression of hnRNPL to promote the metastasis of cancer cells." (PMID 36087568, 2022). "The regulatory mechanisms of SNHG1 in cancers have been widely studied." (PMID 36213821, 2022). "SNHG1 expression was increased in cancer cells compared with SV-HUC-1 cells." (PMID 36230661, 2022). "Therefore, the changes in some ferroptosis-related genes were explored, wherein, SNHG1/7 was found to not only regulate many FA metabolism related-genes, but also mediate cancer cell ferroptosis." (PMID 36195833, 2022). "The oncogenic role of SNHG1 has been elucidated in various cancers." (PMID 36230661, 2022).
cancer (continued). "Additionally, lncRNA small nucleolar RNA host gene 1 (SNHG1) also functions as an oncogene in various human cancers." (PMID 33450825, 2021). "They mainly summarized the relationship between SNHG1 and cancer and revealed that SNHG1 may act as a useful biomarker for the diagnosis, prognosis and treatment of human cancer." (PMID 34717631, 2021). "Prominently, SNHG1 could epigenetically suppress gene expression through recruiting EZH2 in various cancers." (PMID 34806925, 2021). "Our results confirmed that SNHG1 was up-regulated in pan-Cancer and TCGA-BRCA datasets." (PMID 34806925, 2021). "SNHG1 has been well-studied in different types of cancers due to its oncogenic role." (PMID 34899268, 2021). "We first analyzed the expression of SNHG1 in pan-Cancer and TCGA-BRCA datasets." (PMID 34806925, 2021). "Moreover, overexpression of SNHG1 was found in other cancers and modulate the expression of other miRNAs." (PMID 33009370, 2020). "SNHG1 was also described as an important modulator of cancer progression." (PMID 32947877, 2020). "Moreover, as a member of small nucleolar RNA host lncRNA family, SNHG1 acts as a useful tumor biomarker for cancer diagnosis, prognosis, and treatment." (PMID 33552958, 2020). "Several studies have revealed that SNHG1 expression is abnormally elevated in cancer cells and may function as an oncogene to promote cancer progression." (PMID 32497022, 2020). "Consistent with previous research, SNHG1 were upregulated in various kind of cancer." (PMID 33009370, 2020). "As an oncogenic lncRNA, SNHG1 is overexpressed in different types of cancer." (PMID 31693735, 2019). "The combined results indicated that elevated SNHG1 expression level was significantly associated with poor OS (HR = 2.06, 95% CI: 1.69–2.52, P < 0.01) and PFS (HR = 2.78, 95% CI: 1.69–4.55, P < 0.01) in various cancers." (PMID 31391030, 2019). "Therefore, we conducted the present quantitative meta-analysis to investigate the prognostic value of SNHG1 in various cancers." (PMID 31391030, 2019). "Other researchers found six aberrantly expressed lncRNAs in HCC tissues with respect to the corresponding normal tissues; however, only small nucleolar RNA host gene 1 (SNHG1) expression in cancer tissues correlated with the expression levels measured in plasma from the same patients." (PMID 31416190, 2019). "Therefore, we carried out this meta-analysis, including 10 studies and 1129 patients, to explore the relationships between SNHG1 expression and the clinical pathologic parameters and prognosis in human cancers." (PMID 31008944, 2019). "The present meta-analysis demonstrated that upregulation of lncRNA SNHG1 might serve as a useful prognostic biomarker in various cancers." (PMID 31008944, 2019). "We also demonstrated that enforced SNHG1 expression was a predictor of worse outcome in digestive system (HR = 2.04, 95% CI: 1.56–2.68, P < 0.01) and non-digestive system (HR = 2.09, 95% CI: 1.55–2.83, P < 0.01) cancer patients." (PMID 31391030, 2019). "The results from stratified analysis turned out that enforced SNHG1 expression was predictive of worse outcome in digestive system (HR = 2.04, 95% CI: 1.56–2.68, P < 0.01) and non-digestive system (HR = 2.09, 95% CI: 1.55–2.83, P < 0.01) cancer patients." (PMID 31391030, 2019). "However, most studies reported the prognostic value of SNHG1 in cancer patients was limited by small sample size." (PMID 31391030, 2019). "Small nucleolar RNA host gene 1 (SNHG1) is critical in the progression of cancers." (PMID 31469189, 2019). "SNHG1 is a well-studied oncogenic lncRNA in different types of cancer." (PMID 31693735, 2019). "These are all about the tumorigenesis function of SNHG1 in different cancers." (PMID 29575772, 2019). "SNHG1 was reported to be involved in the tumorigenesis and progression of several cancers recently." (PMID 29416759, 2018). "Right panel, CCK-8 assays demonstrated that silence of SNHG1 inhibited cancer cell growth." (PMID 30266084, 2018).
cancer (continued). "Moreover, SNHG1 has manifested oncogenic attribute in different kinds of cancers; nevertheless, the genes influenced by the SNHG1 continue to remain uncertain." (PMID 29970899, 2018). "Moreover, through analyses of RNA sequencing data in TCGA, we found SNHG1 was upregulated in most cancers." (PMID 30266084, 2018). "In addition, flow cytometry was used to analyze cell cycle distribution of SNHG1 knockdown cancer cell." (PMID 29340086, 2017). "In addition, we have emphasized the clinical significance of SNHG1 in cancers in our article." (PMID 37684619, 2023). "Blockade of the SNHG1-HDAC interaction may be a potential target for cancer therapy in NB." (PMID 36130928, 2022). "Because the stemness of cancer cells is preferentially associated with aggressive forms of cancer, our finding may provide a molecular explanation as to why SNHG1 is over-expressed in ~95% of MIBCs but not in non-muscle-invasive bladder cancers." (PMID 36077697, 2022). "However, very little is known about whether SNHG1 participates in the stem-cell-like and invasive properties of cancer cells and, if so, what signaling pathway conducts such effects." (PMID 36077697, 2022). "Finally, six lncRNAs (DLEU2, HOTTIP, MALAT1, NEAT1, SNHG1, and TUG1), registered in Lnc2Cancer 2.0, a database offering comprehensive experimentally supported associations between lncRNA and human cancer, were selected as candidate lncRNAs for the diagnosis of HCC." (PMID 34185961, 2021). "In addition, previous studies showed that SNHG1 could function as ceRNA, playing a vital role in cancer development." (PMID 32802839, 2020). "Taken together, SNHG1 could serve as biomarker for the prognosis of patients with cancer." (PMID 31008944, 2019). "Therefore, targeting SNHG1 may be an optional strategy for treatment of AML or other types of cancers." (PMID 31615767, 2019). "Similarly, EdU results revealed that silencing of KLF2 and CDKN2B could partially rescue SNHG1 knockdown induced reductions in cancer cell proliferative capacity." (PMID 30266084, 2018). "Small nucleolar RNA host gene 1 (SNHG1), situated on 11q12.3, is pivotal in the progression and prognostication of numerous cancer types." (PMID 40387409, 2025). "SNHGs are a family of lncRNAs derived from snoRNAs, and SNHG1, SNHG5, and SNHG20 have been reported to participate in tumor prognosis in various cancers." (PMID 38553452, 2024). "DLEU2, HOTTIP, and SNHG1 have also been reported as onco-lncRNAs in HCC, while LINC00853 is currently poorly understood for the role in cancer and deserved for further study." (PMID 37006626, 2023). "LncRNAs (SNHG1, POU3F3, and RP11-323N12.5) regulate cancer cell immune evasion by mediating the differentiation and distribution of Tregs14." (PMID 37646231, 2023). "Several of these lncRNAs in the risk model have been reported to play significant roles in different cancers, such as CCR5AS, LINC01749, TMEM220-AS1, KCNMA1-AS1, SNHG1, and LINC01672." (PMID 37686677, 2023). "Small nucleolar RNA host gene 1, or SNHG1, is an lncRNA that is over-expressed in a broad range of cancer types." (PMID 36077697, 2022). "Meanwhile, miR-216b-5p was bound by SNHG1 and LINC00518 which has been shown to regulate cancer cells chemoresistance." (PMID 35152275, 2022). "To date, there are 22 members of the SNHG family (SNHG1 to SNHG22) many of which have been shown to be deregulated in cancer, being critically involved in processes such as cancer cell proliferation, tumor progression, metastasis, and chemoresistance." (PMID 36139687, 2022). "SNHG1 was determined to be an upregulated lncRNA in HCC, and its knockdown delayed the cancer progression in vitro and tumor metastasis in vivo." (PMID 34095464, 2021). "Following the conditions of strict stringency in CLIP data and at least eight cancer types in Pan-Cancer, LRRC75A-AS1, SNHG1, NEAT1, and MIRLET7BHG were predicted to bind with miR-330-5p." (PMID 33771969, 2021).